ENSG00000222966
Synonyms: LOC124900245
Gene: Small nucleolar RNA gene on chromosome 7 (99,952,033 to 99,952,158, forward strand). Ensembl gene ENSG00000222966.
Gene Ontology:
Biological process: RNA processing
Cellular component: nucleolus
Homologues: Paralogues in human: SNORA40B (75% identical), SNORA40 (75% identical), SNORA40C (74% identical).